LINC02068 (long independently transcribed non-coding RNA 2068)
Gene: Long non-coding RNA gene on chromosome 3 (172,552,287 to 172,595,607, reverse strand). Ensembl gene ENSG00000223387.
Diseases named in the same sentence as LINC02068 in open-access papers:
LINC02068 is named in the same sentence as 1 disease in open-access papers, as found by Europe PMC text mining. Sharing a sentence is not in itself a finding about the gene and the disease.
LINC02068 shares sentences with these, for which no sentence is quoted: endometrial cancer (1 paper).